JAK2 (Janus kinase 2)
Diseases named in the same sentence as JAK2 in open-access papers (continued):
Sharing a sentence is not in itself a finding about the gene and the disease.
Huntington disease (4 papers, 2018 to 2025). Huntington disease (HD) is a rare neurodegenerative disorder of the central nervous system characterized by unwanted choreatic movements, behavioral and psychiatric disturbances and dementia. "A recent study in Huntington’s disease patients showed that reactive astrocytes activated via the JAK2/STAT3 pathway were able to reduce the toxic huntingtin protein aggregation in neurons." (PMID 37219933, 2023). "IL-6-mediated JAK2/STAT3 signaling cascade has been shown to contribute to neurodegeneration in AD and Huntington’s disease models." (PMID 33494411, 2021).
inflammatory skin disease (4 papers, 2013 to 2024). Inflammatory skin disorders covers a broad category that includes many conditions ranging in severity, from mild itching to grave medical health complications These disorders are common in people of all ages and races. "Suppression of pSTAT3 following topical application of JAK-1/2 inhibitor in cutaneous inflammation has been reported, encouraging hopes that selective JAK inhibitors may play a role in treating inflammatory skin disease as well as JAK2 translocation associated neoplasia." (PMID 23372669, 2013). "CBD’s potential as a JAK2 inhibitor opens new avenues for the development of targeted therapies for a variety of inflammatory skin diseases, offering a safer and more specific alternative to existing treatments." (PMID 39335596, 2024).
intracerebral hemorrhage (4 papers, 2021 to 2026). A cerebrovascular disorder characterized by bleeding into one or both cerebral hemispheres including the basal ganglia and the cerebral cortex. "In contrast, JAK2-CHIP exhibited inverse associations with intracerebral hemorrhage and atrial fibrillation, whereas DNMT3A-CHIP was positively associated with atrial fibrillation and inversely associated with abdominal aortic aneurysm." (PMID 42131836, 2026). "However, after intracerebral hemorrhage, increased expression of integrin β1 in the brain significantly improved neurobehavioural score with decrease of neutrophil infiltration through JAK2/STAT1 pathway." (PMID 33564320, 2021).
laryngeal squamous cell carcinoma (4 papers, 2021 to 2026). A squamous cell carcinoma that arises from the larynx. "Curcumin also prevented VEGF and MMP-2 production in laryngeal squamous cell carcinoma cells by reducing JAK2 and STAT3 phosphorylation and inhibiting angiogenesis." (PMID 37463912, 2023). "In addition, curcumin has also been shown to inhibit VM in squamous cell carcinoma of the larynx through the inhibition of the Janus kinase-2 (JAK-2)/signal transducer activator of transcription protein (STAT) signaling pathway, and the downregulation of MMP-2 and VEGF expression." (PMID 35887002, 2022). "In laryngeal squamous cell carcinoma, curcumin inhibited the expression of JAK2 and phosphorylation of STAT3, which is JAK2-dependent." (PMID 34867402, 2021).
mastocytosis (4 papers, 2017 to 2024). A clonal myeloproliferative neoplasm characterized by the proliferation and accumulation of neoplastic mast cells in one or multiple organs or organ systems. "For example, mastocytosis with JAK2 mutation defines mastocytosis as associated with a chronic myeloproliferative disease or with chronic myelomonocytic leukemia." (PMID 39456668, 2024). "For example, the presence of JAK2 V617F will raise the suspicion of an MPN/MDS, and detection of KIT D816V is usually associated with an underlying mastocytosis." (PMID 29088721, 2017).
non-alcoholic fatty liver disease (4 papers, 2016 to 2024). "The JAK2/STAT5 pathway links the downregulation of CircScd1 in non-alcoholic fatty liver disease (NAFLD) to the advancement of fatty liver disease." (PMID 39120276, 2024). "Besides, simvastatin also significantly enhanced p-JAK2 expression in the liver in the progression of non-alcoholic fatty liver disease in rats." (PMID 35955474, 2022).
non-alcoholic steatohepatitis (4 papers, 2022 to 2024). "An FXR activator blocked nonalcoholic steatohepatitis-dependent HCC progression by suppressing the SOCS3/Jak2/STAT3 pathway." (PMID 35999582, 2022).
non-Hodgkin lymphoma (4 papers, 2012 to 2020). Distinct from Hodgkin lymphoma both morphologically and biologically, non-Hodgkin lymphoma (NHL) is characterized by the absence of Reed-Sternberg cells, can occur at any age, and usually presents as a localized or generalized lymphadenopathy associated with fever and weight loss. "Other putative JAK2 translocations include SSBP2-JAK2 in pre-B ALL, PAX5- and STRN3-JAK2 in childhood ALL and SEC31A-JAK2 in classical non Hodgkin lymphoma." (PMID 22384256, 2012).
ovarian tumor (4 papers, 2009 to 2024). "Jak2, and Kit were also upregulated in response to E2 and altered in 12 % and 8 % of ovarian tumors, respectively." (PMID 26879975, 2016). "We have previously shown that ascites-derived ovarian tumor cells isolated from recurrent patients treated with chemotherapy have significantly higher expression of activated JAK2/STAT3 pathway compared to the tumor cells isolated from the ascites of chemonaive patients." (PMID 29682172, 2018).
parasitic infections (4 papers, 2019 to 2024). "In the process of parasite infection, the JAK2/STAT3 signaling pathway also has a vital role." (PMID 31745105, 2019). "Given the wealth of data on JAK2 inhibitors and the fact that one such inhibitor, Ruxolitinib (targets JAK1/2) has a European Union patent that is expected to expire in August 2027 and the US patent is expected to expire in December 2027 offers opportunity for use in parasitic disease treatment." (PMID 39817173, 2024).
prostate tumors (4 papers, 2018 to 2024). "Additionally, inhibition of Jak2 with the drug AZD1480 blocked Jak2-STAT5a/b signaling and suppressed prostate tumor growth in both cell culture and mouse models." (PMID 30558204, 2018). "Subsequent work reported that activation of Janus kinase-2/signal transducer and activator of transcription-3 (Jak2/Stat3) pathway in PTEN-null senescent prostate tumors established an immunosuppressive tumor microenvironment thereby leading to its growth and chemoresistance." (PMID 31137607, 2019). "Analysis of RNAseq data for 52 normal prostate (control) and 498 prostate adenocarcinoma obtained from TCGA database, revealed that LEP, LEPR, JAK2 and STAT3 are statistically significant downregulated in prostate tumors in relation to normal (control) prostate." (PMID 31671654, 2019). "As with other carcinomas, Jak/STAT core components, IL-6, Jak2, and STAT5, and other key regulators of this pathway are implicated in promotion of prostate tumor growth and metastasis, and there is no highly effective treatment to cure metastatic disease." (PMID 30558204, 2018).
Pruritus (4 papers, 2023 to 2025). Pruritus is an itch or a sensation that makes a person want to scratch. "The underlying mechanism of pruritus in LP remains unknown; however, similar responses were seen with topical JAK1/2 inhibition with topical ruxolitinib, implying that JAK1 and/or JAK2 play a central role in LP pruritus." (PMID 39541169, 2024). "Cytokines including IL-31, IL-4, IL-13, and TSLP are crucial for pruritus in AD transmit their signals into the cells via JAK-1 and JAK-2." (PMID 36983094, 2023).
sarcoidosis (4 papers, 2021 to 2024). Sarcoidosis is a multisystemic disorder of unknown cause characterized by the formation of immune granulomas in involved organs. "Hence, we treated the macrophage granuloma aggregates of sarcoidosis patients with Tofacitinib, a JAK2/3 inhibitor that was shown to be effective in treating patients with longstanding cutaneous sarcoidosis." (PMID 38353578, 2024). "We identified 34 genes with a possible role in the etiology of sarcoidosis, including JAK2." (PMID 33903979, 2021). "Currently, the reports of JAKi in treating sarcoidosis have primarily used tofacitinib orally, a JAK1/JAK3 inhibitor, or ruxolitinib, a JAK1/JAK2 inhibitor, topically." (PMID 39345281, 2024). "We also found that the activity of other cytokines including GM-CSF (JAK2), IL-15 (JAK1/3), IL-6 (JAK1/2), IL-12 (JAK2/TYK2) and TNF (JAK-independent) are also evident in sarcoidosis." (PMID 35668129, 2022).
T-cell leukemia (4 papers, 2008 to 2025). A malignant disease of the T-lymphocytes in the bone marrow, thymus, and/or blood. "AZ960, which is also a JAK2 inhibitor, has shown promising results in inducing growth arrest and apoptosis in adult T-cell leukemia cells." (PMID 40777132, 2025).
Ureteral obstruction (4 papers, 2019 to 2022). Obstruction of the flow of urine through the ureter. "We studied the role of JAK2/STAT3 in a model of congenital obstructive nephropathy using unilateral ureteral obstruction (UUO) in neonatal mice at the second day of life." (PMID 31846485, 2019).
uveitis (4 papers, 2021 to 2025). An inflammatory process affecting a part of or the entire uvea. "Inflammatory cytokines, such as IL-6, which transduces cell signaling through the JAK/STAT pathway, and TNF, whose expression is reduced by inhibition of JAK1 and JAK2, are considered to be associated with the pathology of JIA-uveitis and ANA-positive uveitis." (PMID 34627340, 2021). "Despite sharing the same JAK2 mutation, P2 exhibited uveitis and fever, whereas P3 did not." (PMID 40616106, 2025). "In the mouse model of uveitis, inhibition of the JAK/STAT signaling pathway by SOCS1-KIR, which binds to JAK2, could suppress and ameliorate experimental autoimmune uveitis (EAU)." (PMID 34966823, 2021).
abdominal aortic aneurysm (3 papers, 2023 to 2026). Enlargement and ballooning of the vessel that supplies arterial blood to the abdomen, pelvis and legs. "More recently, a cross-sectional study among 39 MPN patients with JAK2 V617F found that nine patients (23%) exhibited the presence of thoracic (7/9) and/or abdominal aortic aneurysms (2/9)." (PMID 39062663, 2024). "A study of human arterial tissue also showed that blocking JAK2/STAT3 pathway could attenuate the progress of abdominal aortic aneurysm." (PMID 37089432, 2023). "Additionally, subjects with clonal hematopoiesis of indeterminate potential (CHIP) with the JAK2 V617F somatic variant had a >12-fold increase in the risk of TAA (but not abdominal aortic aneurysms) compared to those without JAK2 V617F CHIP." (PMID 39062663, 2024).
adenomyosis (3 papers, 2023 to 2024). The growth of endometrial tissue inside the muscular wall of the uterine corpus. "Curiously, though, patients with adenomyosis display distinct JAK2/STAT3 pathway states in various tissues." (PMID 39886033, 2024). "The downregulation of the JAK2/STAT3 pathway corresponded with the low expression of KLF4 in the endometrial tissue of adenomyosis." (PMID 39886033, 2024). "However, adenomyosis disrupts this equilibrium, where an increase in IL-6 levels leads to the activation of the JAK2/STAT3 pathway, fostering EMT and enhancing cellular invasion capabilities." (PMID 39595579, 2024). "According to our analysis, endometrial decidualization problems in patients with adenomyosis are brought on by aberrant pathways in the endometrial stromal cells of adenomyosis, including PI3K/Akt, JAK2/STAT3, and hedgehog." (PMID 39886033, 2024). "These insights underscore the potential of targeting the JAK2/STAT3 pathway—both its upstream and downstream components—as a strategy to slow adenomyosis progression." (PMID 39595579, 2024). "In general, the formation of adenomyosis lesions involves the activation of JAK2/STAT3, and the development of adenomyosis lesions can be inhibited by blocking this route." (PMID 39886033, 2024).
alcoholic fatty liver disease (3 papers, 2019 to 2025). Lipid infiltration of the hepatic parenchymal cells that is due to alcohol abuse. "Moreover, we found that kefir peptides improved non-alcoholic fatty liver diseases through manipulation of the JAK2/STAT3 and JAK2/AMPK signaling pathways in a high fructose-induced fatty liver animal model." (PMID 32472055, 2020). "The findings collectively indicate that inhibition of the JAK2/STAT3 pathway mitigates stress-induced hepatic inflammatory injury by reprogramming macrophage polarization dynamics, aligning mechanistically with Jinmei Yao’s observations in non-alcoholic steatohepatitis models." (PMID 41369337, 2025).
amyloidosis (3 papers, 2019 to 2024). A disorder characterized by the localized or diffuse accumulation of amyloid protein in various anatomic sites. "Several studies have linked the JAK/STAT pathway to amyloidosis and AD, and our molecular docking results showed that GS-Rd can interact directly with JAK2 and STAT3, suggesting that GS-Rd may exert anti-AD activity by regulating Aβ deposition through the modulation of the JAK/STAT pathway." (PMID 36588689, 2022).
atrial fibrillation (3 papers, 2021 to 2026). A disorder characterized by an electrocardiographic finding of a supraventricular arrhythmia characterized by the replacement of consistent P waves by rapid oscillations or fibrillatory waves that vary in size, shape and timing and are accompanied by an irregular ventricular response. "Significant associations between JAK2 and the occurrence of atrial fibrillation (AF) are observed in the healthy population." (PMID 40607626, 2025).
blood disease (3 papers, 2015 to 2023). A disease that occurs in the blood. "Therefore, the JAK2/TET2/HOXA9 motif shares all the required properties for observing a clinical divergence in blood diseases." (PMID 36192425, 2022).
bone marrow failure (3 papers, 2021 to 2024). "As homozygous deletion of Jak2 in hematopoietic cells has been shown to severely impair HSC function and lead to fatal bone marrow failure, we generated NrasG12D mice with heterozygous deletion of Jak2." (PMID 35352806, 2022).
cardiomyopathy (3 papers, 2024 to 2026). A disease of the heart muscle or myocardium proper. "Our findings illustrate that PatA mitigates the effects of HG + PA- or STZ-induced cardiomyopathy by acting on the JAK2/STAT3 signaling pathway." (PMID 38794201, 2024). "In conclusion, our study elucidates that PatA ameliorates HG + PA- or STZ-induced cardiomyopathy through the modulation of the JAK2/STAT3 signaling pathway." (PMID 38794201, 2024).
diabetic cardiomyopathy (3 papers, 2023 to 2025). Diabetic cardiomyopathy is a disorder of the heart muscle in people with diabetes. "Thus, the JAK2/STAT3 pathway may be considered to be of vital importance in ameliorating the effects of OMT against diabetic cardiomyopathy." (PMID 36597092, 2023).
dilated cardiomyopathy (3 papers, 2022 to 2025). Cardiomyopathy which is characterized by dilation and contractile dysfunction of the left and right ventricles. "In this study, bioinformatics analyses and multiomics techniques were employed to elucidate the molecular mechanisms underlying dilated cardiomyopathy (DCM) and to identify five potential biomarkers: VCL, ABCB1, JAK2, KDR, and NGF." (PMID 40217309, 2025). "Conditional deletion of Jak2 in cardiomyocytes results in dilated cardiomyopathy, similar to the phenotype reported here for conditional loss of Jak1, indicating indispensable and nonredundant functions for both JAK1 and JAK2 in cardiac myocytes." (PMID 40744288, 2025).
endometriosis (3 papers, 2018 to 2025). The growth of functional endometrial tissue in anatomic sites outside the uterine body. "Upregulation of JAK2(Janus kinase 2)/signal transducer and activator of transcription 3 pathway has also been observed in endometriosis." (PMID 39821173, 2025). "In summary, our data suggest a potential role of STIP1 in endometriosis susceptibility, which may occur through the modulation of MMP-9 functions in a fashion independent of several known signaling proteins, such as NF-kB, ERK, AKT, and JAK2." (PMID 29304094, 2018). "The JAK2 protein is part of the JAK2/STAT3 signaling pathway, which is important for migration and invasion abilities of endometriotic cells in endometriosis." (PMID 31169291, 2019).
esophageal adenocarcinoma (3 papers, 2016 to 2022). A malignant tumor with glandular differentiation arising predominantly from Barrett mucosa in the lower third of the esophagus. "Leptin stimulates the growth of cancer cells, including esophageal adenocarcinoma cell lines, through the activation of janus kinase 2 (JAK2) and p38 mitogen-activated protein kinase (p38MAPK) pathways." (PMID 33513939, 2021).
Glomerular sclerosis (3 papers, 2021 to 2023). Accumulation of scar tissue within the glomerulus. "It has been reported that the glomeruli and tubulointerstitium of patients with DKD have significantly higher expression of JAK1-3, STAT1 and STAT3 mRNA, and protein, particularly JAK2, which activates JAK/STAT signaling and induces glomerular sclerosis and tubulointerstitial fibrosis." (PMID 37635867, 2023).
hepatitis B (3 papers, 2015 to 2024). "The recurrent presence of JAK2, especially in the hepatitis B and influenza A pathways, highlights its pivotal role and positions it as a key target for future molecular docking studies aimed at exploring the molecular interactions between A. annua compounds and this protein." (PMID 39598448, 2024).
hypercalcaemia (3 papers, 2018 to 2025). "Although classic PV is characterized by trilineage proliferation (panmyelosis), several JAK2‐positive cases with isolated erythroid hyperplasia have been reported, particularly in the context of secondary stimuli such as hyperparathyroidism‐induced hypercalcemia." (PMID 41321895, 2025). "Of 20,086 and 9,570 diagnostic requests for the JAK2 V617F mutation and BCR-ABL1 fusion respectively, 59 requests (0.2 %) were received for investigation of either JAK2 V617F (n=35), BCR-ABL1 (n=12) or both (n=12), with the sole clinical details provided of hypercalcemia." (PMID 31611758, 2019). "Despite these criteria, hypercalcemia in the absence of other clinical or laboratory features of an MPN has become a periodic, if infrequent prompt for molecular testing of the BCR-ABL1 fusion and/or the JAK2 V617F." (PMID 31611758, 2019).
hyperhomocysteinemia (3 papers, 2008 to 2025). A serious metabolic condition caused by mutations in the MTHFR gene, medications, or nutritional deficiency. "The present study investigated the possible role of Janus kinase-2 (JAK-2) in hyperhomocysteinemia-induced attenuation of cardioprotective effect of ischemic preconditioning (IPC)." (PMID 21593984, 2008).
Hyperinsulinemia (3 papers, 2022 to 2025). An increased concentration of insulin in the blood. "It is worth noting that hyperinsulinemia has been shown to suppress the JAK2/STAT5 signaling pathway." (PMID 37189668, 2023). "DIO rats had lower hepatic JAK2 protein levels but higher IRS-1 levels than control rats due to hyperinsulinemia." (PMID 37189668, 2023).
immune thrombocytopenia (3 papers, 2019 to 2023). "The JAK2 agonist Eltrombopag is licensed for the treatment of immune thrombocytopenia." (PMID 38133879, 2023).
Infertility (3 papers, 2021 to 2024). "Studies have reported that leukemia inhibitory factor (LIF) and its JAK2/STAT3 signaling pathway are among the pathways most closely associated with infertility due to abnormal endometrial receptivity." (PMID 38896093, 2024). "Several previous reports have demonstrated that CE decreases the level of LIF, thus causing the abnormal function of the JAK2/STAT3 signaling pathway, which affects endometrial receptivity and ultimately leads to embryo implantation failure and is a possible pathogenesis of CE infertility." (PMID 38896093, 2024). "The activation of IL‐6/JAK2/STAT1 and STAT3 signaling pathways are found in the hydrosalpinx in infertile patients, indicating that they might be involved in the pathogenesis of hydrosalpinx." (PMID 37382258, 2023). "In the current study, we hypothesized that BSZY-D could improve the HPRL infertility through PRLR deubiquitination, targeting JAK2/STAT5 pathway and its downstream kisspeptin of hypothalamus." (PMID 34424219, 2021).